MYH7 (myosin heavy chain 7)
Diseases named in the same sentence as MYH7 in open-access papers (continued):
Sharing a sentence is not in itself a finding about the gene and the disease.
myocarditis (6 papers, 2015 to 2025). Myocarditis is a condition that is characterized by inflammation of the heart muscle (myocardium). "Notably, the Lutokhina study, which was incorporated intoour review, revealed a higher prevalence of mutations in the MYH7 geneamong patients diagnosed with myocarditis in combination with HCM compared tothose with isolated HCM." (PMID 40351682, 2025). "Our differential gene analysis did detect MYH7 and MYH6, and MYH6 was also among the hub genes of the severe myocarditis cohort." (PMID 36286305, 2022). "When DBA/2 mice with the MYH7 S545A variant and BALB/c mice without the variant are auto-inoculated with cardiac myosin, chronic myocarditis only occurs when serum from the DBA/2 strain is injected into DBA/2 not BALB/c mice." (PMID 29510741, 2018).
Ventricular arrhythmia (6 papers, 2020 to 2025). "A recent meta‐analysis reported that myosin the MYH7 mutation group showed the highest rate of ventricular arrhythmia compared with the MYBPC3, TNNT2, and TNNI3 mutation group." (PMID 32815161, 2020). "In addition, the genotype–phenotype relationship in PLN patients is not distinctly different from those caused by other causal genes (MYBPC3/MYH7), but these patients could carry a high risk for ventricular arrhythmia." (PMID 38392255, 2024). "Also, TNNI3 mutation carriers have lower survival than MYBPC3 and MYH7 mutation carriers, and TNNC1 mutation carriers have a higher risk of developing fatal ventricular arrhythmias." (PMID 38540296, 2024).
arrhythmogenic right ventricular cardiomyopathy (5 papers, 2017 to 2026). "Two of them were described before: DSP variant as unclassified in proband with arrhythmogenic right ventricular cardiomyopathy and MYH7 variant as possibly pathogenic but coexisting with another possibly pathogenic variant in LDB3 gene in proband with familial dilated cardiomyopathy." (PMID 28045975, 2017). "Genetic variants in desmosomal proteins (e.g., PKP2, DSP, DSG2, DSC2) are strongly associated with arrhythmogenic right ventricular cardiomyopathy (ARVC), while mutations in sarcomeric and cytoskeletal genes (e.g., MYH7, LMNA, DES) are linked to hypertrophic and dilated cardiomyopathies." (PMID 41596321, 2026).
channelopathies (5 papers, 2019 to 2024). "The variants included three channelopathy-associated genes (RYR2, CACNA1C, and ANK2), three HCM- or DCM-associated genes (MYH7, LDB3, and PRKAG2), five ACM-related genes (PKP2, JUP, DSG2, DSP, and TMEM43), and two cardiac transcription factor genes (TBX5 and GATA4)." (PMID 39272661, 2024).
hyperthyroidism (5 papers, 2014 to 2024). Overactivity of the thyroid gland resulting in overproduction of thyroid hormone and increased metabolic rate. "The corresponding mutated genes set that has common effects on hyperthyroidism in children included IGF1, CACNA1S, MYH7, IL6, TTN, CACNB2, LAMA2, and DMD." (PMID 37876543, 2023). "The expression levels of Mhrt, Brg1 and Myh6/Myh7 have been assessed in rat models of hyperthyroidism or acute myocardial ischemia/reperfusion (IR) treated with T3 replacement therapy." (PMID 32987653, 2020). "In contrast to rodents, reports on cardiac MYH7 expression in human subjects with hypo- and hyperthyroidism are limited." (PMID 24781449, 2014). "On the other hand, the upregulation of SERCA2 and downregulation of MYH7 due to hyperthyroidism may hamper heart contractile dysfunction in SHRs." (PMID 31374823, 2019).
myocardial infarction (5 papers, 2012 to 2025). Gross necrosis of the myocardium, as a result of interruption of the blood supply to the area, as in coronary thrombosis. "Analysis of the noncoding transcripts originating from the myosin heavy chain 7 (Myh7) locus, an important structural protein required for heart contractions, revealed that one, the lncRNA Mhrt, was down-regulated after induced myocardial infarction." (PMID 27007508, 2016). "Similarly, the mouse-Geneformer model predicted that deletion of genes Nppb, Ankrd1, and Myh7 from myocardial infarction cells would also lead to a transition towards a normal state." (PMID 40106407, 2025). "The mouse-Geneformer similarly indicated that activation of Ankrd1 and deletion of Myh7 could lead to a comparable transition from normal heart cells towards myocardial infarction cells." (PMID 40106407, 2025). "The original human-Geneformer predicted that activation of NPPB and ANKRD1, as well as deletion of MYH7, could drive normal heart cells towards myocardial infarction state." (PMID 40106407, 2025).
myocardial diseases (4 papers, 2022 to 2025). "The expression of its encoding genes, MYH6 and MYH7, is implicated in regulatory processes governing cardiac function and is also significantly altered in various myocardial diseases." (PMID 36157891, 2022). "In general, MYH7-associated disorders are exceptionally heterogenous and can present as skeletal myopathies, with or without myocardial disease." (PMID 39485824, 2025). "The two genes uniquely identified for single AF events have been shown important for myocardial diseases and cardiac abnormalities, coding for functions found to be central in malformation in heart (NKX2-5) and myosin (MYH7)." (PMID 38725839, 2024).
RASopathies (4 papers, 2019 to 2023). "We evaluated the functional criteria (PS3/BS3) of six VCEPs (CDH1, Hearing Loss, Inherited Cardiomyopathy-MYH7, PAH, PTEN, RASopathy)." (PMID 31783775, 2019). "Due to the genetic heterogeneity of HCM, a comprehensive panel should be used for screening that covers not only the main sarcomeric culprits (e.g., TNNT2, MYH7, MYBPC3, TNNI3, ACTC), but also other causes including RASopathies, mitochondrial proteins, and glycogen storage diseases." (PMID 37180798, 2023).
cardiac arrest (3 papers, 2019 to 2023). Cessation of breathing and/or cardiac function. "Genetic testing was performed for the proband and two of his siblings and a niece of the proband, who suffered a cardiac arrest at the age of nine, all being MYH7 mutation positive." (PMID 37509704, 2023). "Herein we describe the case of Myh7 mutation-induced HCM and cardiac arrest in a patient and evaluated information originating from genetic background to guide ICD administration." (PMID 35004917, 2021).
congestive heart failure (3 papers, 2017 to 2022). Failure of the heart to pump a sufficient amount of blood to meet the needs of the body tissues, resulting in tissue congestion and edema. "In human suffering from chronic heart failure, decrease of MHC-I encoded by MYH7 but increase of MHC-IIb was detected in costal diaphragm." (PMID 28407751, 2017).
Danon disease (3 papers, 2020 to 2025). A lysosomal glycogen storage disease characterized by severe cardiomyopathy and variable degrees of muscle weakness, frequently associated with intellectual deficit. "The dilated phenotype subgroup (P.1–P.10) included all patients with Danon disease, the patient with a homozygous ALPK3 variant, carriers of in-frame deletions in TTN and FLNC, a heterozygous TRIM63 missense variant, and carriers of splice-site variants in MYH7 and MYBPC3." (PMID 41440877, 2025).
hypothyroidism (3 papers, 2014 to 2021). Abnormally low levels of thyroid hormone. "Basic experiments have reported that hypothyroidism suppresses myosin heavy chain 6 protein expression and enhances myosin heavy chain 7 protein expression and that hypothyroidism induces cardiac atrophy as a result." (PMID 34733168, 2021). "Third, although MYH7 expression was shown to be increased with hypothyroidism, unliganded TR per se is not a transcriptional activator." (PMID 24781449, 2014). "The expressions of myh7 and Serca2a genes are lower in cardiac MED13 knockout (MED13-cKO) mice than wild-type mice 82, suggesting that cardiac MED13 plays a role in cardiac function conservation in hypothyroidism, as myh7 and Serca2a expressions are necessary to maintain normal cardiac function." (PMID 33390853, 2021).
sarcopenia (3 papers, 2025). Progressive decline in muscle mass due to aging which results in decreased functional capacity of muscles. "MYH7 (blue-labeled) fast-twitch fibers were markedly reduced in SAMP8 mice, consistent with the pathological feature of fast fiber loss observed in sarcopenia patients." (PMID 41220805, 2025).
Sepsis (3 papers, 2017 to 2024). Sepsis is defined as life-threatening organ dysfunction caused by a dysregulated host response to infection. "Because IL-1β treatment leads to decreased Myh2, Myh4, and Myh7 expression in myocytes, reduced muscular MyHC expression during sepsis might be caused by IL-1β." (PMID 28097512, 2017). "Our finding indicating that IL‐13 restores the sepsis‐induced decrease in expression of Mb, Tnni1, and Myh7 at the transcriptional level would support the potential roles of IL‐13 in improving or preserving muscle atrophy and weakness in sepsis." (PMID 39016179, 2024). "Similar to those in skeletal muscles of sepsis mice, expression of Mb, Tnni1, and Myh7 mRNAs was downregulated, while that of IL‐13RA1 was upregulated in LPS‐stimulated C2C12 myotubes." (PMID 39016179, 2024). "MYH6 and MYH7 appear to be the only upregulated proteins during the late stage of sepsis-induced kidney injury." (PMID 28246552, 2017). "Whereas sepsis led to a decreased Myh2 and Myh7 expression in muscle of WT, this effect was blunted in Nlrp3 KO." (PMID 28097512, 2017). "Tnni1 and Myh7 directly regulate muscle contraction and decreased expression of these proteins may be involved in muscle weakness in sepsis." (PMID 39016179, 2024). "Together, these results imply that the downregulation of key proteins associated with slow‐twitch skeletal muscle, such as Mb, Tnni1, and Myh7, may contribute to aggravating muscle weakness and wet weight reduction in WT, compared with PD‐1‐KO, sepsis survivor mice." (PMID 39016179, 2024). "In three spots found higher and abundant in 48 h sepsis, myosin-6 (“MYH6”) from spots ID 57 and ID 73 and myosin-7 (“MYH7”) from spot ID 71 were identified." (PMID 28246552, 2017).
Barth syndrome (2 papers, 2016 to 2025). Barth syndrome (BTHS) is an inborn error of phospholipid metabolism characterized by dilated cardiomyopathy (DCM), skeletal myopathy, neutropenia, growth delay and organic aciduria. "Several genes have been implicated in LVNC, including those responsible for encoding sarcomeric proteins (TTN and MYH7), cytoskeletal proteins (P121L), genes related to nuclear membrane components, chaperones, and the TAFAZZIN gene, causing Barth syndrome." (PMID 40004439, 2025).
breast carcinoma (2 papers, 2018 to 2024). "Furthermore, the discovery of certain proteins (MYH2, MYL1, MYL2, MYH7) and microRNAs (hsa-let-7d-5p) linked to the advancement of breast cancer offers new, prospective biomarkers for diagnosis and therapy, opening the door for innovative therapeutic approaches." (PMID 39656775, 2024). "The PPI study revealed hub proteins such as MYH2 and MYH7, demonstrating the role of cytoskeletal components in breast cancer etiology." (PMID 39656775, 2024).
cardiac conduction disease (2 papers, 2020 to 2024). "In a large meta-analysis of 31 studies with 6123 HCM patients, MYBPC3 variant carriers (20% of all HCM patients) had less cardiac conduction disease, less ventricular arrythmia and less HTx (present in 15%, 20% and 0.6% of all MYBPC3 variant carriers respectively) compared to MYH7 variant carriers." (PMID 38836037, 2024).
diabetic cardiomyopathy (2 papers, 2024 to 2025). Diabetic cardiomyopathy is a disorder of the heart muscle in people with diabetes. "Cluster 4 was enriched in genes of the ‘heart contraction’ (e.g., ACTC1, MYL3 and ACTA1) and ‘diabetic cardiomyopathy’ (e.g., TNNI3, MYH7 and GAS6)." (PMID 37766635, 2024).
Fabry disease (2 papers, 2019 to 2026). Fabry disease (FD) is a progressive, inherited, multisystemic lysosomal storage disease characterized by specific neurological, cutaneous, renal, cardiovascular, cochleo-vestibular and cerebrovascular manifestations. "The final diagnoses included FD (classic), aHUS, and HCM (Fabry disease and MYH7 variants)." (PMID 41695170, 2026).
familial cardiomyopathy (2 papers, 2015 to 2018). An instance of cardiomyopathy that is caused by an inherited modification of the individual's genome. "A novel myosin heavy chain 7 mutation (E848G) identified in a familial cardiomyopathy was studied in patient-specific induced pluripotent stem cell–derived cardiomyocytes." (PMID 30623132, 2018). "In the current study, we encountered both of these challenges when studying an African-American familial cardiomyopathy (FCM) with adult-onset systolic dysfunction associated with a rare MYH7 E848G variant (rs727504311)." (PMID 30623132, 2018). "Two hot spots (TNNI3-p.Arg145Gly, and LMNA-p.Arg190Trp) and double (LMNA-p.Arg190Trp plus MYH7-p.Arg1045His) heterozygous mutations were found to be highly correlated with familial cardiomyopathy." (PMID 26199943, 2015). "Many nonsynonymous variations were detected in the familial cardiomyopathy patients and per nonsynonymous variation in coverage of more than 30x, including three pathogenic heterozygotic mutations (TNNI3, c.433C>G, p.Arg145Gly; LMNA, c.568C>T, p.Arg190Trp; and MYH7, c.3134G>A, p.Arg1045His)." (PMID 26199943, 2015).
gynecological cancer (2 papers, 2017 to 2023). "Our approach has identified “actin (ACTA1)” and “myosin (MYH7)” combination with “MYBPC1” as the potential pathways causing promoter changes in gynecological cancers." (PMID 28927463, 2017). "It is evident that the MYH7 gene has many copies reported in the COSMIC datasets as well as in the TCGA datasets suggesting it a potential biomarker for four gynecological cancer types." (PMID 28927463, 2017). "Expression of ACTA1, MYH7, and MYBPC1 may be a potential promotor of gynecological cancer initiation or progression." (PMID 38248716, 2023).
Insulin resistance (2 papers, 2020 to 2021). Increased resistance towards insulin, that is, diminished effectiveness of insulin in reducing blood glucose levels. "Specific slow type myosin heavy chain components were associated with AL (MYH7) and BI (MYH3) pigs, while an overexpression of MAP3K14 in AL may be associated with their lower loin proportion, induced insulin resistance, and increased inflammatory response via NFkB activation." (PMID 34065673, 2021).
ischemic cardiomyopathy (2 papers, 2013 to 2025). Ischemic cardiomyopathy is a cardiomyopathy in which a weakness in the muscle of the heart due to inadequate oxygen delivery to the myocardium with coronary artery disease being the most common cause. "Based on the bioinformatics analysis, Myh6, Myh7, and Fn1 were selected to have pivotal roles in cardiac cell contraction and ischemic cardiomyopathy." (PMID 40271502, 2025). "Using exon array, the global mRNA splicing profile of ischemic cardiomyopathy has been investigated, and the alternative splicing of four main sarcomere genes, such as cardiac troponin T (TNNT2), cardiac troponin I (TNNI3), myosin heavy chain 7 (MYH7), and filamin C, gamma (FLNC), was dysregulated." (PMID 23766705, 2013).
myocardial ischemia (2 papers, 2025). A disorder of cardiac function caused by insufficient blood flow to the muscle tissue of the heart. "Enhanced Myh7 and Nf1 were found in the heart of myocardial ischemia rat model in compression with the normal group." (PMID 40271502, 2025). "Postn, which is upregulated in myocardial remodeling after myocardial ischemia, was increased in the MYH7 Q315R/ + group." (PMID 41237118, 2025).
myofibrillar myopathy (2 papers, 2017 to 2025). "Truncating variants in TTN are strongly associated with DCM, while mutations in DSP, LMNA, MYH7, RBM20, TNNT2, BAG3, and FLNC (the latter being linked to myofibrillar myopathy) are also commonly implicated." (PMID 39857686, 2025).
neuropathy (2 papers, 2018 to 2021). A disorder affecting the nervous system that manifests with pain, tingling, numbness, and/or muscle weakness. "Three of these now have a confirmed genetic diagnosis (MYH7 and TTN genes in the neuropathy group and MYOT in the IBM group)." (PMID 29997562, 2018).
Sinus bradycardia (2 papers, 2022 to 2024). Bradycardia related to a mean resting sinus rate of less than 50 beats per minute. "As it was observed that variants in this gene were independent risk factors for adverse events, our patients with MYH7 variants were among the severely affected cases, both of whom presented with sinus bradycardia." (PMID 35893073, 2022). "A symptomatic sinus bradycardia was an indication for pacemaker implantation in P6 (novel MYH7 pathogenic c.323G>A p.(Arg108His) variant)." (PMID 35893073, 2022). "Among those who developed symptoms of HF (LVEF reduction and LV enlargement) were patients P9 (novel pathogenic PRDM16 complex rearrangement c.1286_1289delinsTTGCACTT p.(Gly429Valfs*176)) and P7 with additional sinus bradycardia (novel likely pathogenic MYH7 c.3973-2A>C p.?" (PMID 35893073, 2022). "Still, some gene mutations, such as NOTCH genes, ACTC1, MYH7, MYBPC3, TTN, and HCN4, among others, have been implicated with the HCN4 gene responsible for sinus bradycardia in some patients." (PMID 39677872, 2024).
type 2 diabetes (2 papers, 2015 to 2025). "The exact mechanisms underlying the increase in myosin super-relaxation may be complex, but are likely to involve type 2 diabetes-specific hyper-glycated residues on the coiled-coil region of MYH7." (PMID 40295335, 2025). "We identified several AGE-modified peptides arising from myosin heavy chain type I (MYH7) protein obtained from patients with type 2 diabetes that were absent in the control participants." (PMID 40295335, 2025).
advanced heart failure (1 paper, 2025). Patients with advanced heart failure have severe limitations, experiences symptoms even while at rest and are mostly bedbound patients. "Both individuals with the MYH7 recurrent pathogenic missense variant were diagnosed after the age of 70; however, one presented with advanced heart failure and left ventricular dysfunction." (PMID 40453736, 2025).
alcohol abuse (1 paper, 2018). The use of alcoholic beverages to excess, either on individual occasions ("binge drinking") or as a regular practice. "Interestingly, the variants identified in EPS8L3 (rs148185176), MYH7, CRX (rs139340178), and SELENOO, were also present in two relatives with alcohol abuse (individuals 6 and 18)." (PMID 30379966, 2018).
atherosclerosis (1 paper, 2023). A disease characterized by the build-up of fatty material and calcium deposition in the arterial wall resulting in partial or complete occlusion of the arterial lumen. "Likewise, when PERI-cell-derived constructs were supplemented with 800 μM vitamin C, MYH7 was downregulated, as was the matrixmetalloproteinase-encoding gene MMP12, which is a macrophage metalloelastase commonly implicated in atherosclerosis." (PMID 38069418, 2023).
Bradycardia (1 paper, 2020). A slower than normal heart rate (in adults, slower than 60 beats per minute). "Additionally, training stimulates the expression of Nppa and Myh7 only in WT/CKO mice, and this can further contribute to the development of bradycardia." (PMID 33348907, 2020).
chronic kidney disease (1 paper, 2016). Impairment of the renal function secondary to chronic kidney damage persisting for three or more months. "Changes of Myh 6, Myh7 and Myh11 phosphorylation suggest that dysregulation of cytokinesis may be associated with salt sensitivity in chronic kidney disease." (PMID 27775022, 2016).
chronic tonsillitis (1 paper, 2016). "We performed real-time PCR (qRT-PCR) to assess mRNA levels of ERR-α and Myh7 in palatopharyngeal tissues isolated from patients with OSAS or patients with chronic tonsillitis (control)." (PMID 27250523, 2016).
endocardial fibroelastosis (1 paper, 2021). Endomyocardial fibroelastosis is a cause of unexplained childhood cardiac insufficiency. "For example, genes (e.g., TAZ, NEX, MYH7, and CSRP3) have been demonstrated to involve the development of endocardial fibroelastosis." (PMID 34469078, 2021).